ENSG00000262304 (novel readthrough SHPK-TRPV1 protein)
Gene: Protein-coding gene on chromosome 17 (3,585,149 to 3,636,249, reverse strand). Ensembl gene ENSG00000262304.
Genetic constraint (gnomAD): Missense variants: 668 observed, 667.66 expected, observed/expected ratio (o/e) 1, 90% interval 0.94 to 1.07. Synonymous variants: 290 observed, 282.11 expected, observed/expected ratio (o/e) 1.03, 90% interval 0.93 to 1.13.